GFAP (glial fibrillary acidic protein)
Diseases named in the same sentence as GFAP in open-access papers (continued):
Sharing a sentence is not in itself a finding about the gene and the disease.
Cognitive impairment (continued). "Of the seven patients treated with steroids and IVIG, only one failed to improve and continued to struggle with cognitive deficits 10 months after his diagnosis of GFAP astrocytopathy and after extending monthly IVIG, mycophenolate mofetil and oral steroids." (PMID 33569363, 2020). "The levels of GFAP and vimentin in CSF did not correlate with the severity of the cognitive impairment in PDD or DLB." (PMID 22577599, 2012). "In addition to GFAP, TSPO binding increased proportional to increased GFAP expression secondary to sepsis and 18F-FDG PET imaging showed decreased uptake in line with reduced GFAP expression secondary to 27-hydroxycholesterol-induced cognitive impairment." (PMID 40485663, 2025). "Moreover, higher baseline GFAP levels have been found to predict the development of mild cognitive impairment (MCI) within four years, suggesting that GFAP could serve as a useful indicator of cognitive progression in PD, especially in the TD subtype." (PMID 41465278, 2025). "As such, serum NfL and GFAP appear not to be sensitive biomarkers for cognitive impairment in PCS." (PMID 38438479, 2024). "However, we found a significant increase in CSF-EVs expressing two of the neuronal-associated markers, GFAP and CD200, in HIV+ individuals with cognitive impairment group compared to those without cognitive impairment." (PMID 36601110, 2022). "On the other hand, STG protected against cognitive deficits through improving oxidative stress biomarkers, inflammatory mediators, lipid profiles, and hippocampus level of BDNF as well as decreasing caspase-3 and GFAP and increasing Ki-67 immunoreactions in the hippocampus." (PMID 35265716, 2022). "No studies have been done in patients with mild cognitive impairment (MCI) investigating whether plasma GFAP can predict future conversion to AD dementia, specifically." (PMID 33773595, 2021). "However, further research is needed to clarify whether the reduction in cognitive impairment due to AST-120 is a direct result of changes in hippocampal aquaporin-4 and glial fibrillary acidic protein levels or a secondary effect of decreased uremic toxin levels." (PMID 39595807, 2024). "Its small-to-moderate correlations with hippocampal volume and cognitive scores indicates that plasma GFAP is not a robust indicator of neurodegeneration and cognitive impairment; however, plasma GFAP might be of prognostic value in predicting future cognitive decline." (PMID 37924152, 2023). "For example, glial fibrillary acidic protein (GFAP) is shown to increase significantly in the hippocampus (HP) of aged rats both with and without cognitive impairment." (PMID 28785724, 2017). "Similarly, the blood concentrations in GFAP and NFL were not affected by 6 months of aerobic training in older adults with no cognitive impairment." (PMID 38803456, 2024). "Here, we report increased GFAP levels in the dlPFC and PCC of AD patients compared to those with no cognitive impairment, reinforcing the utility of GFAP as a blood-based biomarker in AD and confirming that measures collected from the periphery reflect processes happening in the CNS." (PMID 39580758, 2024). "In attempts to explain this finding, neurodegenerative biomarkers like neurofilament light chain (NfL) and glial fibrillary acidic protein (GFAP) were measured and found to be higher in COVID-19 patients than non-COVID-19 patients with mild cognitive impairment or AD." (PMID 39456822, 2024).
Alexander disease (186 papers, 2010 to 2026). "Alexander disease (AxD) is a rare and fatal neurodegenerative disorder caused by dominant mutations in the gfap gene, which encodes glial fibrillary acidic protein (GFAP), a major intermediate filament in astrocytes." (PMID 42196383, 2026). "For instance, CSF GFAP shows superior diagnostic performance for Alexander disease (AxD) compared to plasma GFAP." (PMID 39289040, 2025). "Alexander disease (AxD) is a leukodystrophy caused by sporadic GFAP mutations, being hence primary astrocytopathy." (PMID 40744926, 2025). "The glial fibrillary acidic protein (GFAP) gene is mutated in Alexander disease, a rare neurological condition." (PMID 40002678, 2025). "These insights hold significant implications for Alexander disease arising from deletion mutations in GFAP." (PMID 40076540, 2025). "This unexpected finding led to the discovery that mutations in the GFAP gene cause Alexander disease (AxD)." (PMID 40076540, 2025). "Alexander Disease (AxD) arises from dominant mutations in the gene encoding glial fibrillary acidic protein (GFAP), an astrocytic intermediate filament." (PMID 41315317, 2025). "For instance, single point mutations in GFAP can cause Alexander disease (AxD), a rare and fatal disorder of astrocytes that primarily affects children." (PMID 40735838, 2025). "Alexander disease (AxD) is a fatal neurodegenerative disorder caused by gain-of-function glial fibrillary acidic protein mutations." (PMID 40064497, 2025). "Alexander disease (AxD) is a rare astrocytic neurodegenerative disorder classified as a leukodystrophy and caused by mutations in the GFAP gene." (PMID 41438969, 2025). "Alexander disease, associated with glial fibrillary acidic protein (GFAP) sporadic mutations, is characterized by the accumulation of Rosenthal fibers in astrocytes, resulting in the destruction of white matter." (PMID 40744926, 2025). "Looking at some rarer diseases and syndromes, in Alexander’s disease there is a clear role for astrocytes due to the pathological variants in the GFAP gene." (PMID 40137462, 2025). "The top two models identified were APP/PS1 transgenic mice expressing mutant APP and PSEN1, and mice carrying a GFAP mutation that is causative of Alexander disease, a primary disorder of astrocytes in the CNS." (PMID 38236817, 2024). "Alexander disease is a rare neurodegenerative disorder resulting from pathogenic variants in the GFAP gene." (PMID 39420046, 2024). "Alexander disease (ALXDRD) is a rare neurodegenerative disorder of astrocytes resulting from pathogenic variants in the GFAP gene." (PMID 39420046, 2024). "Alexander disease (AxD) is an intractable neurodegenerative disease caused by mutations in glial fibrillary acidic protein (GFAP), which is predominantly expressed in astrocytes." (PMID 39596168, 2024). "A similar distribution was observed for the other variant, rs59285727 (17:44915251C > T) in GFAP, linked to the juvenile form of Alexander disease." (PMID 39498263, 2024). "In a mouse model of Alexander disease, a CNS degenerative disorder caused by mutations in GFAP, we found that protoplasmic astrocytes of the hippocampus and isocortex became CD44+ as the disease progressed." (PMID 38247821, 2024). "The second best model and ranked fourth and fifth overall was an Alexander disease associated GFAP mutation (R236H) in adult mice at day 56 in hippocampus and corpus collosum, respectively." (PMID 38236817, 2024). "For example, Alexander disease, driven by mutations in GFAP gene with pathological astrogliosis and neurodegeneration, is commonly associated with TDP-43 proteinopathy." (PMID 37935530, 2023). "Alexander disease (AxD) is a rare autosomal dominant astrogliopathy caused by mutations in the gene encoding for glial fibrillary acidic protein." (PMID 37396762, 2023). "GFAP encodes a glial intermediate filament protein that is generally associated with Alexander disease, a rare AD leukodystrophy with progressive neurological disease." (PMID 37234784, 2023).
Alexander disease (continued). "Glial contributions to pathology can be primary (for example, astrocytic expression of mutant glial fibrillary acidic protein, GFAP, causing Alexander disease) or secondary, when glial cells react to pathology by mounting context-specific defensive responses." (PMID 37828019, 2023). "GFAP - a heterozygous variant in exon 4 (c.715C>T) causing Alexander’s disease, an autosomal dominant disorder." (PMID 37519562, 2023). "Alexander disease is a neurodegenerative disorder affecting cerebral white matter, resulting from mutations in the protein glial acidic fibrillary protein (GFAP) in astrocytes." (PMID 36421479, 2022). "An overaccumulation of the expression of GFAP has a close causal relationship with the pathogenesis of Alexander's disease." (PMID 36601294, 2022). "Alexander disease (AxD) is a rare and fatal neurodegenerative disorder caused by mutations in the gene encoding glial fibrillary acidic protein (GFAP)." (PMID 34808356, 2022). "GFAP aggregation is also associated with other neurodegenerative conditions diagnosed in infants, such as Alexander disease or Giant Axonal Neuropathy." (PMID 35053415, 2022). "GFAP mutations, favoring aggregation to form Rosenthal fibers, are both causal and diagnostic for chronic gliosis, as found in Alexander’s disease, and several single-nucleotide polymorphisms in GFAP are strongly associated with this demyelination disorder." (PMID 35890250, 2022). "In particular, Alexander disease is caused by astrocyte dysfunction due to a dominant mutation in GFAP and iNOS overactivation." (PMID 35822835, 2022). "Mutations in GFAP lead to Alexander disease, a genetic disorder characterized by fibrinoid degeneration of astrocytes, demyelination and white matter anomalies (MIM 203450)." (PMID 35606419, 2022). "Alexander disease is a leukodystrophy caused by mutations and subsequent overexpression of a mutant allele of the glial fibrillary acidic protein (GFAP) gene; which is the major intermediate filament in astrocytes." (PMID 33803137, 2021). "GFAP gain-of-function mutations cause Alexander disease, a rare astrogliopathy characterized by accumulation of GFAP in the central nervous system." (PMID 33481951, 2021). "Modeling Alexander disease using patient iPSC-derived astrocytes has uncovered that GFAP mutations in astrocytes leads to secondary impaired function and proliferation of OPCs." (PMID 33842475, 2021). "For example, Alexander’s disease is a primary astrocytopathy caused by the overexpression of the intermediate filament glial fibrillary acidic protein (GFAP)." (PMID 33757579, 2021). "Alexander disease, which results from mutations in GFAP, is a primary disorder of astrocytes that leads to neurodevelopmental delays and intellectual disability." (PMID 33842475, 2021). "Alexander disease is a rare form of leukodystrophy caused by heterozygous mutations in the gene encoding glial fibrillary acidic protein (GFAP)." (PMID 35003479, 2021). "Alexander disease (AD) is an autosomal dominant disorder caused by mutations in GFAP, encoding the glial fibrillary acidic protein (OMIM# 137780)." (PMID 35096710, 2021). "A direct example of this is seen in Alexander disease where gain of function mutations in glial fibrillary acidic protein (GFAP), which is the major intermediate filament (IF) expressed by astrocytes, causes leukodystrophy and neuronal loss." (PMID 34356161, 2021). "An interesting study was conducted on human pluripotent stem cells (hPSCs) expressing a form of the Alexander disease-associated “astrocytic” gene glial fibrillary acidic protein (GFAP) with a mutation that impairs mitochondrial transfer from astrocytes." (PMID 34638589, 2021). "Alexander disease (AxD) is a rare neurodegenerative disorder that is caused by dominant mutations in the gene encoding glial fibrillary acidic protein (GFAP), an intermediate filament that is primarily expressed by astrocytes." (PMID 33685480, 2021).
Alexander disease (continued). "An example that corroborates this view is the case of Alexander’s disease, a lethal leukodystrophy caused by mutations in the glial fibrillary acidic protein (GFAP) gene, which encodes an astrocytic intermediate filament protein." (PMID 34440788, 2021). "Gain-of-function mutations in GFAP lead to Alexander disease (AxD), which is characterized by a severe reactive astrocyte phenotype, including hypertrophic GFAP+ processes and astrocytic cytoplasmic inclusions of GFAP called Rosenthal fibers." (PMID 34282843, 2021). "Alexander Disease (AxD) is a rare leukodystrophy caused by missense mutations of glial fibrillary acidic protein (GFAP)." (PMID 34046764, 2021). "Alexander’s disease is a rare demyelinating disorder caused by mutations in the gene encoding glial fibrillary acidic protein (GFAP), the major intermediate filament protein of astrocytes, and it is the only known astrocyte-specific disease." (PMID 34638653, 2021). "Glial fibrillary acidic protein (GFAP) mutation resulted in protein aggregation in astrocytes from models of Alexander disease." (PMID 32344649, 2020). "Some parallels can be drawn from the involvement of plectin in Alexander disease, a rare progressive neurodegenerative disorder caused by dominantly acting mutations in GFAP." (PMID 32630739, 2020). "Alexander disease is a neurological disease that causes leukodystrophy and neuronal loss of brain, due to mutation of glial fibrillary acidic protein (GFAP) gene." (PMID 31952467, 2020). "Alexander disease is caused by mutations in the GFAP gene, which encodes for intermediate filaments in astrocytes." (PMID 32793632, 2020). "The other was a de novo variant c.235C > T in GFAP, which was detected in two unrelated patients (Nos.36 and 37) with Alexander Disease." (PMID 33176815, 2020). "The patient’s genetic test resulted in known pathogenic glial fibrillary acidic protein variant, indicating Alexander disease." (PMID 31952467, 2020). "The overexpression of plectin cDNA converted these aggregates to networks composed of thin filaments, whereas the expression of GFAP with the most common Alexander disease mutation lowered plectin levels." (PMID 32630739, 2020). "There is a rare astrocyte disease caused by dominant gain-of-function mutations in the GFAP gene named Alexander disease." (PMID 31316338, 2019). "In Alexander disease, mutated versions of the gene make GFAP collect in disordered clumps or aggregates, which interfere with the astrocytes’ normal activities." (PMID 31682229, 2019). "All Alexander disease patients develop GFAP aggregates, but the type of mutation they have in the gene for GFAP does not predict how their illness will progress." (PMID 31682229, 2019). "In a model of Alexander disease (AxD), a rare neurodegenerative disease caused by autosomal dominant gain of function mutations in GFAP, we recently found extraordinarily large Ca2+ signals in astrocytes, whose areas were over 300 μm2." (PMID 30823575, 2019). "These lower molecular weight GFAP fragments have been detected in brain extracts of Alexander disease patients, a rare nervous system disorder caused by GFAP mutations (M.‐H." (PMID 30667110, 2019). "Alexander disease (AxD) is an extremely rare neurodegenerative disorder caused by glial fibrillary acidic protein (GFAP) gene mutations." (PMID 31611638, 2019). "Mutations in GFAP, encoding the glial fibrillary acidic protein, cause Alexander disease (MIM #203450), which is a disease of the central nervous system." (PMID 31718026, 2019). "Alexander disease is caused by dominantly acting mutations in glial fibrillary acidic protein (GFAP), the major intermediate filament of astrocytes in the central nervous system." (PMID 31838996, 2019). "For example, heterozygous missense mutations of GFAP gene resulted in Alexander disease, a neurodegenerative disorder that affects children typically." (PMID 29746255, 2018).
Alexander disease (continued). "We therefore investigated key mechanosensitive markers in astrocytes differentiated from an Alexander disease iPSC line (GFAP mutation R88C) and a CRISPR/Cas9 gene corrected control line." (PMID 29765022, 2018). "C/C genotype at rs2070935 of the GFAP gene in Alexander disease was associated with an earlier onset and a more rapid progression of ambulatory disability compared with other genotypes." (PMID 29746255, 2018). "Upregulation of lamin A and C in CNS cells has been observed in astrocytes from patients with Alexander disease, which is characterized by a gain-of-function mutation to the GFAP gene." (PMID 30450357, 2018). "Alexander disease is a rare neonatal neurodegenerative disorder caused by accumulation of pathogenic Rosenthal fibers due to mutations in astrocytic GFAP." (PMID 30405400, 2018). "Alexander disease (AxD) is a neurodegenerative disease caused by heterozygous mutations in the GFAP gene, which encodes the major intermediate filament protein of astrocytes." (PMID 28700643, 2017). "Alexander disease (AxD) is a rare hereditary neurodegenerative disorder caused by glial fibrillary acidic protein (GFAP) gene mutations, most of which are missense mutations." (PMID 28690862, 2017). "These MRI findings led us to reconsider the candidacy of c.1126C>T as an Alexander disease GFAP variant." (PMID 27648269, 2016). "Astrocytic GFAP expression is associated with aging and AD; dominant GFAP mutations in Alexander disease cause protein aggregates that contain GFAP, vimentin, plectin, ubiquitin, and small chaperones such as α‐crystallin." (PMID 27448508, 2016). "Paralog annotation, functional analysis, and frequency in Alexander disease cases versus publically available databases have provided substantial evidence that the p.R376W variant in GFAP is indeed responsible for our patient's phenotype." (PMID 27648269, 2016). "Especially, glial process thickenings similar to the Rosenthal fibers that are typical of LCC have been observed in Alexander’s disease, a demyelinating leukodystrophy associated with mutations in the glial fibrillary acidic protein (GFAP)." (PMID 26852234, 2016). "The mouse model led to targeted GFAP sequencing in 11 cases of Alexander disease, 10 of which harbored a genetic variant." (PMID 27648269, 2016). "The predominant genetic cause of Alexander disease was discovered after transgenic GFAP mice presented with astrocyte inclusions that pathologically mimicked the Rosenthal fibers in Alexander disease." (PMID 27648269, 2016). "These cases highlight the need for functional validation of GFAP variants associated with atypical Alexander disease." (PMID 27648269, 2016). "Following the initial discovery of GFAP variants associated with Alexander disease, the functional characterization of newly identified variants was completed in mouse models." (PMID 27648269, 2016). "Alexander disease is a fatal neurodegenerative disease caused by mutations in the astrocyte intermediate filament glial fibrillary acidic protein (GFAP)." (PMID 26378915, 2015). "Alexander disease is a rare neurological disorder caused by mutations in GFAP, yet it is unclear how glial disruptions lead to neural death." (PMID 26608817, 2015). "We further investigated three additional Alexander disease-associated mutant forms of GFAP, GFAPR239H, GFAPL352P and GFAPA364P." (PMID 26608817, 2015). "Consistently, the expression of a mutated form of GFAP in the astroglial compartment reduced adult neurogenesis and impaired the development of adult-born neurons in a mouse model of Alexander’s disease." (PMID 24748560, 2015). "Alexander disease is caused by dominant mutations in GFAP, an intermediate filament protein of astrocytes." (PMID 26608817, 2015). "There are also genetic mutations that interfere with normal astrocyte function, such as the gain of function mutation in the GFAP gene thought to be responsible for Alexander’s disease." (PMID 26793073, 2015).